IL6 (interleukin 6)
Diseases named in the same sentence as IL6 in open-access papers (continued):
Sharing a sentence is not in itself a finding about the gene and the disease.
skin inflammation (91 papers, 2012 to 2026). "Subcutaneous injection of OVA into the sole of the paw causes skin inflammation, with increased levels of interleukins (IL-1beta, IL6, IL13), cytokines (TNF-alpha), and chemokines (CCL11) in the skin of this region." (PMID 40095628, 2025). "FC alleviated AD apparent symptoms, such as dermatitis score, transepidermal water loss, epidermal thickness, and mast cell infiltration upon declining pro-inflammatory cytokines and mediators, IL-6, IL-5, IL-13, TSLP, and TNF-α." (PMID 37689763, 2023). "Compared with WT mice, KO mice showed an increased susceptibility to P. acnes-induced skin inflammation, as evidenced by higher levels of pro-inflammatory factors such as Cxcl1, Il-1α, Il-1β, Il-6 and Tnf-α in the knockout mice." (PMID 35414779, 2022). "They find that PD-1 loss in CD8 T-cells accelerates dermatitis in a manner depending on IL-6 signaling, suggesting IL-6 as a potential therapeutic target." (PMID 33060784, 2020). "Staphylococcus aureus, the concurrent bacterial infection in AD, can induce IL-6 production from dermal fibroblasts causing skin inflammation." (PMID 22272250, 2012). "In mice model, IL-6 has been shown to be a major cause of a high irritant dermatitis." (PMID 22272250, 2012). "TPA stimulation significantly increased the expression of pro-inflammatory cytokines, including TNF-α and IL-6, which are well-established mediators of skin inflammation." (PMID 41302132, 2025). "The results showed that CBG improved dermatitis severity score, epidermal thickness, and mast cell count and reduced inflammatory cytokines (Tslp, Il1b, Il4, Il6, Il13, Il17, Il18, Il22, and Il33) by qRT-PCR (p < 0.001)." (PMID 39851511, 2025). "BSEC in our present study also showed a similar downward trend of pro-inflammatory markers in the DNCB-induced dermatitis mice, in which increased IL-6 and TNF-α in the DNCB group were suppressed by BSEC." (PMID 39519149, 2024). "In the initial stage of skin inflammation, damaged cells express inflammatory mediators, such as interleukin 6 (IL-6), which can promote the differentiation or proliferation of DCs, T cells, and non-immune cells." (PMID 38256910, 2024). "Numerous studies have reported that IL-1β contributes to skin inflammation in AD and induces IL-6 production both in vitro and in vivo." (PMID 37175425, 2023). "Mast cells in turn can activate neutrophils and can attract keratinocytes, inducing the development of skin inflammation, such as in the psoriatic lesions, through the degranulation and production of various cytokines, including IL-1 and IL-6." (PMID 37509136, 2023). "Reduction in scratching frequency, dermatitis severity and trans-epidermal water loss (TEWL), decreased IL-6, IL-31 and IgEs serum levels." (PMID 37509136, 2023). "Together, inflammatory mediators (IL-17 and CCL20) and SASP factors such as IL-1 and IL-6 function in a self-amplifying loop to induce alopecia and dermatitis in irradiated animals." (PMID 37237461, 2023). "The presence of inflammatory cytokines, such as interleukin-6 (IL-6) and interleukin-10 (IL-10), which are both indicators of dermatitis, was also tested for." (PMID 38665149, 2023). "In particular, IL-6 and IL-8 cytokines, which are reportedly produced by keratinocytes during the acute phase of skin inflammation in dermatitis and other skin diseases, were significantly reduced." (PMID 37376157, 2023). "Another study showed that T-MSC injection in an AD mouse model reduced skin inflammation, mast cell infiltration, IgE production, and inflammatory cytokines such as IL6 and TNF-α." (PMID 38201284, 2023). "Compared with normal mice, jet-lagged mice were more sensitive to P. acnes-induced skin inflammation, as evidenced by higher levels of pro-inflammatory factors such as Cxcl1, Il-1α, Il-1β, Il-6 and Tnf-α." (PMID 35414779, 2022).
skin inflammation (continued). "Compared with wild-type mice, Rev-erbα-/- mice showed an increased sensitivity to P. acnes-induced skin inflammation, as evidenced by higher levels of pro-inflammatory factors such as Cxcl1, Il-1α, Il-1β, Il-6 and Tnf-α in the knockout mice." (PMID 35414779, 2022). "Imiquimod (IMQ)-induced psoriasis-like skin inflammation model reduces the suppressive activity of Treg, and then upregulates IL-17 and IL-6, and downregulates IL-10 and FOXP3, whereas butyrate can reverse these progressions by inhibiting HDACs." (PMID 36817115, 2022). "Mangiferin, obtained from Mangifera indica, can ameliorate the skin lesions prominent in dermatitis by reducing the inflammatory biomarkers such as IL-6, TNF-α, and IL-1β." (PMID 35626720, 2022). "In keratinocytes, the CO2-induced suppression of TNFα and IL-6 expression was dependent on the pH of the culture medium, indicating that extracellular pH exerts important effects on skin inflammation." (PMID 33431967, 2021). "Crossing ΔKerOTULIN mice onto a TNFR1-deficient background completely prevented dermatitis, even at old age, and ΔKerOTULIN-TNFR1−/− mice showed significantly reduced IL6, TNF, and IL17 levels in their serum." (PMID 34625556, 2021). "Other studies highlighted the anti-inflammatory role of Nrf2 signaling in reducing the levels of IL-1β and IL-6 to alleviate skin inflammation besides suppressing the activation of inflammatory NF-κB and NLRP3 pathways." (PMID 33424605, 2020). "Taken together, these results suggest that IL-6 acts to ameliorate epidermal hyperplasia during skin inflammation by reducing IL-22-induced keratinocyte proliferation." (PMID 31781680, 2019). "Malt1-KO mice that develop skin inflammation were found to have increased serum levels of the pro-inflammatory cytokines IL-2, IL-4, IL-6, IL-17, IFN-γ, and TNF." (PMID 31632405, 2019). "In fact, during skin inflammation and wound healing, IL-6 has been shown to promote skin repair and regeneration." (PMID 31781680, 2019). "We found that the most relevant cytokines for the oxazolone model were IL-1β, TNFα, IL-4, and IL-6, which shared more than 25% of their variation with the variation in ear thickness in all dermatitis induced mice." (PMID 28290517, 2017). "In conclusion, our data show that R7 enhances the release of IL-6 in undifferentiated primary keratinocytes, which may have consequences for skin inflammation, defense against pathogens, and wound healing." (PMID 40461723, 2025). "Dermatitis caused by DNCB and RID both exhibit similar pathological features (ulceration, dermal thickening, inflammation, follicular dropout, sebaceous gland dropout, etc.)and molecular expressions (increased inflammatory factors IL-6 and TNFα)." (PMID 39519149, 2024). "In vitro, we found that BsAb HB0043 could inhibit the production of IL-6 and IL-8 by NHDFs, more potently than single mAbs, supporting dual target therapy in difficult-to-treat skin inflammation." (PMID 39600699, 2024). "By comparing the expression levels of IL-6 and PGE2 in HaCaT cells, we found that the levels of IL-6 and PGE2 produced by SLS stimulation in HaCaT cells were decreased by ATLE, which indicates that A. truncatum leaves have a therapeutic effect on skin inflammation caused by SLS." (PMID 37007019, 2023). "It is hypothesized that propionate and HFD may not induce the generation of Foxp3+ Tregs in imiquimod-induced dermatitis, which might contain a large amount of IL-6, IL-1β, or IL-23 counteracting their generation." (PMID 37762500, 2023). "Initiation of skin inflammation by P. acnes involves activation of inflammatory cells, monocytes, keratinocytes and sebocytes and subsequent secretion of inflammatory cytokines and chemokines such as IL-1α, IL-1β, IL-6, IL-8 and TNF-α 43-45." (PMID 35414779, 2022).
skin inflammation (continued). "In line with this, dermatitis scores, dorsal IL-6 production, and serum histamine level were more lowered by treatment with 10 mg/kg of RXA than 20 mg/kg of RXA, indicating RXA may be advantageous to manage the skin inflammation." (PMID 35002730, 2021). "Moreover, blockade of interleukin (IL)-6 signaling by anti-IL-6 receptor blocking antibody (MR16-1) restrained the PD-1 signal blockade provoked by severe dermatitis by inhibiting both Th17 cell differentiation and cytotoxic CD8 T cell activation." (PMID 33060784, 2020). "Thus, this highlights the significance of IL-6 blockade therapy specifically for the regulation of PD-1 signal blockade-induced dermatitis." (PMID 33060784, 2020). "Results from this work suggests that IL-6 might play a role in regulating the IL-22/IL-22Rα system during skin inflammation." (PMID 31781680, 2019). "It is interesting to note that the relationship between IL-6 and the IL-22/IL-22Rα system in the context of skin inflammation is unknown." (PMID 31781680, 2019). "We studied the synergistic effects of RR on keratinocytes and demonstrated that RR potently suppressed skin inflammation by inhibiting expression of pro-inflammatory cytokines, such as IL-6 and IL-1β in TNF-α/INF-γ-induced human keratinocytes and 3D human skin tissue model." (PMID 30901835, 2019). "The HIGH and the LOW phenotypes from the conventional mice were clearly transferred to germ-free mice, as there was a higher expression of dermatitis score, ear thickness, IL-1β, TNFα, IL-4, and IL-6 in the HIGH mice compared to the LOW mice, and for most of these also higher than the CONV mice." (PMID 28290517, 2017). "The ant-inflammatory and immunodulatory actions of Exc-B have been observed in TPA-induced inflammation and dermatitis in murine skin, as well as in LPS-induced mouse bone marrow-derived dendritic cells, with the reduction of IL-6 and TNF-α protein expressions." (PMID 28067799, 2017). "Numerous studies have demonstrated that probiotics can alleviate skin inflammation and enhance skin barrier function in AD patients by promoting the activity of regulatory T cells (Tregs) and suppressing the production of pro-inflammatory cytokines, including IL-6 and TNF-α." (PMID 40630180, 2025). "Dermatitis is an inflammatory cutaneous condition where the disease progression is thought to involve a complex interaction of various inflammatory cytokines, such as interleukin-6 (IL-6) and tumor necrosis factor-alpha (TNF-α), along with the accumulation of oxidative stress." (PMID 39519149, 2024). "Previous studies have shown that IL-6 was an important immunomodulatory signal essential for the repair of UV radiation damage to the skin through induction of IL-10 and for limiting dermatitis following irritant contact through deregulation of IL-22R expression." (PMID 33804336, 2021). "Moreover, genetically modified mice lacking PD-1 expression only on CD8 T cells developed accelerated dermatitis, moreover, blockade of IL-6 signaling by anti-IL-6 receptor antibody could ameliorate the dermatitis." (PMID 33060784, 2020). "Additionally, specific deletion of MyD88 in DCs prevented the development of dermatitis with decrease expression of the proinflammatory cytokines IL-6 and IL-12, and different B cell-stimulating cytokines, including IL-10 with hampered B cell proliferation in MRL.Faslpr mice." (PMID 31546763, 2019). "Hence, IL-6 seems to play a key role in the innate component of IL-17-driven PP-like dermatitis, and blockade of IL-6 activity may result in dramatic clinicopathological improvements despite the persistent activation of the IL-17 signaling." (PMID 25126586, 2014). "Our study demonstrated that HPs effectively modulated the production of IL-1β, IL-6, and TNF-α, resulting in a significant reduction in UV-induced skin inflammation." (PMID 38539828, 2024).
skin inflammation (continued). "In the context of skin inflammation, inflammatory cytokines such as TNF-α, IL-17A, and IL-22 induce keratinocytes to produce proinflammatory cytokines, including IL-1β, IL-6, TNF-α, and IL-23, which subsequently influence the liver to increase SAA production." (PMID 39519167, 2024). "EHMF treatment significantly reduced IL-6, TNF-α, and IL-17 levels in the HaCaT skin photoaging cell model, effectively decreasing skin inflammation." (PMID 39469625, 2024). "In conclusion, our findings suggest the potential for dermatological applications of S. polyrhiza and suggest that its anti-dermatitis action is related to the inhibition of TNF and IL-6 by luteolin and luteolin glycosides." (PMID 37686078, 2023). "Oral propionate reduced inflammatory infiltrates and epidermal Ki67+ cells and reduced mRNA levels of IL-17A, IL-17F, IL-17C, IL-22, IL-1β, IL-6, TNF-α, CXCL1, CCL20 and increased those of TGF-β1and IL-10 in imiquimod-indued dermatitis." (PMID 37762500, 2023). "Oral propionate decreased mRNA expression of IL-17A, IL-17C, IL-17F, IL-22, IL-6, IL-1β, TNF-α, CXCL1, and CCL20 in imiquimod-induced dermatitis in comparison between NDIS versus NDIP." (PMID 37762500, 2023). "In summary, our findings suggest the potential for dermatological applications of S. polyrhiza, and that its anti-dermatitis activity is related to the inhibition of TNF and IL-6 by luteolin and luteolin glycosides." (PMID 37686078, 2023). "Oral propionate and the HFD reduced mRNA expression of IL-17A, IL-17C, IL-17F, IL-22, IL-1β, IL-6, TNF-α, CXCL1, CXCL2, and CCL20 in imiquimod-induced dermatitis." (PMID 37762500, 2023). "The transcription factors further regulate the expression of pro-inflammatory genes, such as IL-6 and TNF-α, which ultimately leads to dermatitis." (PMID 35979232, 2022). "Propionibacterium acnes in the skin activate toll-like receptor-2 (TLR-2) and promote the secretion of inflammatory factors such as IL-6, IL-8, and TNF-α, thereby inducing skin inflammation." (PMID 36817115, 2022). "In addition, ROS could induce the nuclear factor kappa light chain enhancer of activated B cells (NF-κB) to translocate to the nucleus, where it can upregulate pro-inflammatory genes, such as interleukin 6 (IL-6) and cyclooxygenase-2 (COX-2) and cause skin inflammation and redness." (PMID 36139829, 2022). "For UV-induced skin disorders, paeonol ameliorates SUV-induced skin inflammation by inhibiting the increase of TOPK, the phosphorylation of p38, JNKs and H2AX, and the secretion of IL-6 and TNF-α in Babl/c mouse." (PMID 35095512, 2021). "Proinflammatory cytokines and chemokines secreted by keratinocytes, such as TNF-α, IFN-γ, IL-1β, IL-6, IL-8, TARC (CCL17), MDC (CCL22), and RANTES, play a very important role in dermatitis." (PMID 34361003, 2021). "Specifically, we observed attenuation of skin inflammation and a significant reduction in expression of mast cell mediators such as CCL2, IL-6, TNFα and MMP9 in the presence of osthole." (PMID 32391014, 2020). "Further evaluation of its anti-inflammatory abilities in vivo revealed that OIR3 exhibited therapeutic effects by inhibiting oxazolone-induced skin inflammation via inhibition of TNF-α, IL-1β and IL-6 mRNA expression." (PMID 31775224, 2019). "Several previous studies have suggested that EPA and DHA diet alleviate ear oedema and inhibit the production of pro-inflammatory factors (IκB, MAPKs, TNF-α, IL-6 and COX-2) in experimental skin inflammation models." (PMID 22873180, 2012). "In addition, bentonite pre-treatment markedly suppressed the secretion of IL-6, IL-8, and CCL2, key mediators of skin inflammation, in keratinocyte cultures (p < 0.05 for all comparisons)." (PMID 41576001, 2026). "Collectively, these findings indicate that Ohwia caudata leaf hydroethanolic extract exerts anti-inflammatory effects through a dual mechanism: downregulation of IL-6 and TNF-α and restoration of TGF-β expression, thereby alleviating TPA-induced skin inflammation." (PMID 41302132, 2025).
skin inflammation (continued). "Furthermore, we examined the level of inflammatory cytokines, including IL-6 and TNF-α, in the DNCB-induced dermatitis animal model." (PMID 39519149, 2024). "The expression levels of IL-1β, IL-4, IL-6, and TNF-α in peripheral blood positively correlate with the severity of dermatitis and may contribute to disease recurrence." (PMID 39748922, 2024). "The DII is correlated with inflammatory biomarkers such as C-reactive protein (CRP), interleukin (IL)-6, and tumor necrosis factor (TNF)-α in various ethnic groups, and those inflammatory biomarkers contribute to the development and progression of dermatitis." (PMID 39464683, 2024). "Considering our results, amplified Th17 responses could have a stronger influence on the development of imiquimod-induced skin inflammation than a decrease in TNF-α and IL-6 in IRF5 KO mice." (PMID 32456211, 2020). "Therefore, it is difficult to conclude which are more important for imiquimod-induced skin inflammation, Th17 cytokines or inflammatory cytokines including TNF-α and IL-6." (PMID 32456211, 2020). "Regarding inflammatory cytokines, imiquimod-induced skin inflammation was reported to be ameliorated but not abolished in IL-17 receptor A-deficient mice and that the inflammation was mediated by TNF-α and IL-6, suggesting their importance in the inflammation." (PMID 32456211, 2020). "The effect of IL-6 on the IL-22-IL-22Rα system in the context of the skin inflammation is, however, not well documented." (PMID 31781680, 2019). "The expression levels of the three inflammatory factors IL-6, MCP-1, and TNF-α in the cells were also significantly decreased, indicating that MMPs in jellyfish venom are probably vital factors leading to jellyfish dermatitis." (PMID 30857352, 2019). "Aryl hydrocarbon receptor (AhR) activation suppresses autophagy and promotes skin inflammation through the NF-Kappa B (NF-κB)/p38 mitogen-activated protein kinase (MAPK) signaling pathway, leading to inflammatory cytokine secretion (IL-1β, IL-6, and TNF-α) in keratinocytes." (PMID 40332377, 2025). "All mice with oxazolone-induced dermatitis had a dramatic increase in IL-1β, IL-4, IL-6, IL-10, TNF-α, IFN-γ, IL-16, IL-17C, IL-17E, IL-17F, IL-21, IL-22, and MIP-3a, whereas the concentrations of IL-12p70, IL-2, IL-17A, and IL-23 were lower in dermatitis mice." (PMID 37889696, 2023). "They produce inflammatory cytokines such as interleukin (IL)-1β, IL-6, IL-8, IL-18, and IL-25 and chemokines such as thymus and activation-regulated chemokine (TARC), cutaneous T cell attracting chemokine (CTACK), and monocyte derived chemokine (MDC) in skin inflammation." (PMID 35626720, 2022). "Additionally, they revealed that ABG extract may act by another mechanism of action by inhibiting the iNOS and COX-2 expression, and thus, prevented the NO, interleukin-6 (IL-6) and TNF-α formation of in LPS-activated RAW264.7 cells and TPA-mediated dermatitis in mice." (PMID 32213941, 2020). "In addition, a reduction in inflammatory cells, decrease in chemokine and inflammatory cytokine expression, and alteration in macrophage mobilization in JP-8-induced dermatitis strongly suggest the role of anti-inflammatory response, rather than inducing IL-6 inflammatory response." (PMID 31992310, 2020).